SLC6A3 (solute carrier family 6 member 3)
Description:
Mediates sodium- and chloride-dependent transport of dopamine. Also mediates sodium- and chloride-dependent transport of norepinephrine (also known as noradrenaline) (By similarity). Regulator of light-dependent retinal hyaloid vessel regression, downstream of OPN5 signaling (By similarity).
Synonyms: DAT; DAT1; PKDYS; PKDYS1
Tractability: Small molecule: an approved drug acts on it; a structure with a bound ligand is known; a high-quality ligand is known; it belongs to a druggable protein family. Antibody: UniProt places it where antibodies can reach, with high confidence; its Gene Ontology location is reachable by antibodies, with high confidence; UniProt predicts a signal peptide or a membrane-spanning region. PROTAC: ubiquitination databases record sites on it; a small molecule that binds it is known.
Target class: SLC superfamily of solute carriers; SLC06 neurotransmitter transporter family; Electrochemical transporter; Transporter
Chemical probes: CHEMBL1643901
Safety:
Unwanted effects reported when the protein is acted on. In parentheses: how it was acted on, where the effect was seen, and who reports it.
acne (Lynch et al. (2017): inhibition, acute dosing, nervous system; Bowes et al. (2012): inhibition, central nervous system)
depression (Lynch et al. (2017): inhibition, acute dosing, nervous system; Bowes et al. (2012): inhibition, central nervous system)
dyskinesia (Bowes et al. (2012): inhibition, central nervous system; Lynch et al. (2017): inhibition, acute dosing, nervous system)
dystonia (Lynch et al. (2017): inhibition, acute dosing, nervous system; Bowes et al. (2012): inhibition, central nervous system)
parkinsonism (Lynch et al. (2017): inhibition, acute dosing, nervous system; Bowes et al. (2012): inhibition, central nervous system)
addictive psychostimulation (inhibition; central nervous system; source: Bowes et al. (2012))
convulsions (inhibition, acute dosing; nervous system; source: Lynch et al. (2017))
decreased motor coordination (activation, acute dosing; nervous system; source: Lynch et al. (2017))
decreased motor strength (activation, acute dosing; nervous system; source: Lynch et al. (2017))
drug abuse/dependence (inhibition, acute dosing; nervous system; source: Lynch et al. (2017))
increased locomotor activity (inhibition, acute dosing; nervous system; source: Lynch et al. (2017))
psychostimulation (inhibition, acute dosing; nervous system; source: Lynch et al. (2017))
seizures (inhibition; central nervous system; source: Bowes et al. (2012))
stereotypy (inhibition, acute dosing; nervous system; source: Lynch et al. (2017))
alcoholism (source: ClinPGx)
no available evidence (source: ClinPGx)
Gene: Protein-coding gene on chromosome 5 (1,392,794 to 1,445,514, reverse strand). Ensembl gene ENSG00000142319.
Subcellular location: Cell membrane; Cell projection, neuron projection; Cell projection, axon
Subcellular location (Human Protein Atlas): Vesicles
Pathways (Reactome):
Disease: Defective neurotransmitter clearance by SLC6A3 causes Parkinsonism-dystonia infantile (PKDYS); Defective transport of neurotransmitters by SLC6A3 causes Parkinsonism-dystonia infantile (PKDYS)
Neuronal System: Dopamine clearance from the synaptic cleft
Transport of small molecules: SLC-mediated transport of neurotransmitters
Gene Ontology:
Molecular function: dopamine:sodium symporter activity; monoamine transmembrane transporter activity; protein binding; neurotransmitter transmembrane transporter activity; amine binding; dopamine binding; heterocyclic compound binding; norepinephrine:sodium symporter activity; protease binding; protein phosphatase 2A binding; protein-containing complex binding; signaling receptor binding; transmembrane transporter activity
Biological process: dopamine uptake; amino acid transport; dopamine uptake involved in synaptic transmission; hyaloid vascular plexus regression; neurotransmitter transport; sodium ion transmembrane transport; neurotransmitter uptake; norepinephrine uptake; response to cAMP; response to ethanol; response to iron ion; response to leptin; response to nicotine; response to xenobiotic stimulus
Cellular component: axon; cell surface; flotillin complex; membrane raft; neuron projection; neuronal cell body; plasma membrane; cytoplasm; membrane; axon terminus; dopaminergic synapse; postsynaptic membrane; presynaptic membrane
Genetic constraint (gnomAD): Loss-of-function variants: 19 observed, 70.94 expected, observed/expected ratio (o/e) 0.27, 90% interval 0.19 to 0.39. The upper end of that interval is the gene's LOEUF score, 0.39, which puts it in group 1 of 6, group 1 being the genes least tolerant of losing a copy. Missense variants: 613 observed, 848.02 expected, observed/expected ratio (o/e) 0.72, 90% interval 0.68 to 0.77. Synonymous variants: 368 observed, 360.37 expected, observed/expected ratio (o/e) 1.02, 90% interval 0.94 to 1.11.
Gene-disease validity (ClinGen):
ClinGen rates the evidence that SLC6A3 causes each of these diseases.
SLC6A3-related dopamine transporter deficiency syndrome (autosomal recessive): Definitive. A complex movement disorder characterized by tremor, rigidity, bradykinesia, chorea, reduced facial expression, and Parkinsonism-dystonia.
Homologues: Orthologues: chimpanzee SLC6A3 (99% identical), mouse Slc6a3 (94% identical), rat Slc6a3 (93% identical), guinea pig SLC6A3 (91% identical), pig SLC6A3 (86% identical), dog SLC6A3 (86% identical), tropical clawed frog slc6a3 (84% identical), macaque SLC6A3 (83% identical), zebrafish slc6a3 (76% identical). Paralogues in human: SLC6A2 (66% identical), SLC6A4 (48% identical), SLC6A5 (41% identical), SLC6A12 (41% identical), SLC6A6 (41% identical), SLC6A8 (40% identical), SLC6A14 (40% identical), SLC6A13 (40% identical), SLC6A7 (40% identical), SLC6A11 (39% identical), SLC6A9 (38% identical), and 6 more.
Diseases named in the same sentence as SLC6A3 in open-access papers:
SLC6A3 is named in the same sentence as 258 diseases in open-access papers, as found by Europe PMC text mining. Sharing a sentence is not in itself a finding about the gene and the disease. The quoted sentences say what the papers report.
Parkinson disease (448 papers, 2004 to 2026). A progressive degenerative disorder of the central nervous system characterized by loss of dopamine producing neurons in the substantia nigra and the presence of Lewy bodies in the substantia nigra and locus coeruleus. "Dysfunction of SLC6A3 leads to the accumulation of dopamine in the synaptic cleft, thereby disrupting normal neural signaling pathways and causing the symptoms of Parkinson’s disease." (PMID 41425581, 2025). "This study investigated the associations of HTR2C rs3813929 and rs518147, HTR6 rs1805054 and SLC6A3 3′UTR VNTR polymorphisms with haloperidol-induced parkinsonism, evaluated using the ESRS, in 229 male patients with schizophrenia." (PMID 36551993, 2022). "Point mutations in the gene encoding the human dopamine transporter (hDAT, SLC6A3) cause a syndrome of infantile/juvenile dystonia and parkinsonism." (PMID 28972153, 2017). "Point mutations in hDAT (SLC6A3) have been linked to a syndrome of dopamine transporter deficiency or infantile dystonia/parkinsonism." (PMID 28405636, 2016). "Of the two Type 2 hits, the SLC6A3 gene encodes a dopamine receptor, also known as DAT, which has been studied mostly in the context of addiction and Parkinson’s disease." (PMID 26466362, 2015). "This patient with clinical features of early-onset Parkinson’s disease was found to be compound heterozygous for SLC6A3 mutations (Ile312Phe, Asp421Asn)." (PMID 24613933, 2014). "Genetic variants of the dopamine transporter gene (SLC6A3 or commonly DAT) have also been implicated in human mental disorders such as parkinsonism, Tourette syndrome, and substance abuse." (PMID 23840506, 2013). "Such small molecules could potentially be useful for the treatment of Dopamine Transporter Deficiency Syndrome (DTDS), a rare genetic form of infantile parkinsonism associated with the misfolding of SLC6A3 dopamine transporter variants." (PMID 40553789, 2025). "Chrna6 and Slc6a3 have neural functions related to dopamine: Chrna6 is associated with nicotine dependence but also affects the activity of dopaminergic neurons; Slc6a3 encodes the dopamine transporter and is involved in multiple neurological conditions ranging from autism to Parkinson’s disease." (PMID 41226761, 2025). "However, to the best of our knowledge, this is the first work that shows that the combination of HTR6 and SLC6A3 risk alleles is associated with the development of haloperidol-induced parkinsonism." (PMID 36551993, 2022). "This review on GLB1, SLC6A3, SLC30A10, SLC39A14, and PLA2G6 is the third MDSGene review series on DYT/PARK genes, following previous articles on DRD genes and X-linked dystonia-parkinsonism." (PMID 40362326, 2025). "This systematic review explores the genotype–phenotype correlations of GLB1, SLC6A3, SLC30A10, PLA2G6, and SLC39A14—recently classified as DYT SLC39A14 and historically linked to dystonia-parkinsonism." (PMID 40362326, 2025). "Our analysis showed dystonia-parkinsonism predominates in SLC6A3 and PLA2G6, while GLB1, SLC30A10, and SLC39A1 show predominantly dystonic phenotypes with a low frequency of parkinsonism." (PMID 40362326, 2025). "SLC6A3, the gene encoding the dopamine transporter (DAT), is deeply influenced by neuroinflammation in Parkinson’s disease." (PMID 39456006, 2024). "Such genomic advances have also allowed the recognition of broader clinical phenotypes associated with SLC6A3, encompassing DTDS parkinsonism-dystonia, early onset parkinsonism, and neuropsychiatric diseases (ADHD and ASD)." (PMID 37443770, 2023). "Solute carrier family 6 member 3 (SLC6A3) involving in the metabolism of dopamine and catecholamine is the potential gene for Parkinson’s disease and alcoholism." (PMID 36186463, 2022). "We have investigated the associations of individual SLC6A3, HTR2C and HTR6 gene polymorphisms; HTR2C haplotypes; as well as the combination of HTR6 and SLC6A3 risk alleles with haloperidol-induced parkinsonism in schizophrenia patients." (PMID 36551993, 2022).
Parkinson disease (continued). "In the 10th injection, down-regulated genes were significantly enriched in terms of “Parkinson’s disease” and “Dopaminergic synapse” (such as Th, Drd2, Slc6a3, and Slc18a2)." (PMID 32997292, 2021). "As a critical regulator of dopaminergic neurotransmission, the human DA transporter (hDAT) gene, SLC6A3, has received enduring attention in candidate gene studies of Parkinson disease and psychiatric diseases." (PMID 34375312, 2021). "In the present study, we also detected that five DEmRNAs, including COX7B2, UBA1Y, VAT1, CYCT and SLC6A3, were enriched in the pathway of Parkinson’s disease." (PMID 31447646, 2019). "We also note that the new Slc6a3 TRAP line is distinct from the one recently used to successfully profile midbrain DA neurons in an MPTP Parkinson’s model." (PMID 28808330, 2017). "Variation in Slc6a3 is associated with idiopathic epilepsy, ADHD, alcohol and cocaine dependence, susceptibility to Parkinson disease, and protection against nicotine dependence." (PMID 27247960, 2016). "The most severe clinical manifestations result from mutations in SLC6A3, SLC6A5, SLCA18, and SLCA19 giving rise to infantile dystonia and parkinsonism (5, –, 7), hyperekplexia (9, –, 11), and Hartnup disease (45, –, 47), respectively." (PMID 25202009, 2014). "Therefore, future studies should analyze the possible interaction between CYP2D6 gene variants and the variants of the SLC6A3, HTR2C and HTR6 genes on the risk for haloperidol-induced parkinsonism." (PMID 36551993, 2022). "This includes a patient with early-onset parkinsonism and attention deficit hyperactivity disorder (ADHD) carrying compound heterozygous missense mutations in SLC6A3 that give rise to I321F and D421N substitutions in the DAT protein." (PMID 34002696, 2021). "This is particularly evident for mutants of the dopamine transporter (DAT/SLC6A3) and of the creatine transporter-1 (CrT1/SLC6A8), which are associated with a syndrome of infantile dystonia/Parkinsonism and intellectual disability/mental retardation, respectively." (PMID 29135937, 2017). "Additionally, the findings indicated a combined effect of HTR6 T and SLC6A3 9R alleles on AIP, with their combination associated with significantly lower scores of ESRS subscale II for parkinsonism, ESRS-based tremor or hyperkinesia and ESRS subscales VI and VIII." (PMID 36551993, 2022). "In addition, we also detected a possible combined effect of HTR6 T and SLC6A3 9R alleles on AIP, with their particular combination associated with significantly lower scores of ESRS subscale II for parkinsonism, ESRS-based tremor or hyperkinesia and ESRS subscales VI and VIII." (PMID 36551993, 2022). "Noteworthy, TH, dopamine receptor 2 (DRD2), SLC6A3/DAT, SLC18A2, tubulin beta 2A (TUBB2A), tubulin alpha 4A (TUBA4A), and tubulin beta 3 (TUBB3) were the 7 key genes enriched in the Parkinson disease pathway." (PMID 40259945, 2025). "Benz had been known to improve Parkinson’s symptoms, mainly as a muscarinic M1 antagonist, as well as a dopamine reuptake inhibitor (DRI), which blocks the action of the dopamine transporter [DAT, also known as solute carrier family 6 member 3 (SLC6A3)]." (PMID 32102440, 2020). "It has been shown that Benz improves Parkinson’s symptoms, mainly as a muscarinic M1 antagonist, as well as a DRI, which blocks the action of the DAT/SLC6A3, while Benz also has affinities with other membrane proteins, including dopamine receptors, histamine receptors, and NET." (PMID 32102440, 2020). "With the exception of SLC6A3 and PLA2G6, which primarily manifest with dystonia and parkinsonism as key features, we found that GLB1, SLC30A10, and SLC39A14 predominantly exhibit a dystonic phenotype, sometimes accompanied by other movement disorders, such as parkinsonism or ataxia." (PMID 40362326, 2025).
Parkinson disease (continued). "We advocate that in adolescents or adults with a clinical picture of juvenile parkinsonism (onset <20 years) investigations for DTDS should be considered, including: (i) CSF neurotransmitter studies; (ii) DAT SPECT scan (abnormal in DTDS); and (iii) SLC6A3 sequencing." (PMID 24613933, 2014).
depression (134 papers, 2004 to 2026). "This SNP alters SLC6A3 expression, which is associated with dopamine levels in the brain and depression severity." (PMID 39420919, 2024). "The SLC6A3 (DAT1) 3′UTR VNTR (rs28363170) polymorphism alters DAT expression, with SS (9R/9R) genotype carriers tending to be associated with a more severe depression course." (PMID 37626766, 2023). "Other studies have linked the SLC6A3 gene mutation with psychiatric disorders such as depression, bipolar disorder, and alcoholism." (PMID 36405903, 2022). "(2015) found that toddlers with at least one A1 allele of DRD2 or with the 10/10 genotype of SLC6A3 had blunted reactive salivary cortisol if their mother had higher depression." (PMID 36282746, 2022). "Studies have found an association between the SLC6A3 gene and personality traits defined by the Cloninger’s model in healthy individuals and patients with depression." (PMID 28182634, 2017). "Β- caryophyllene and dibutyl phthalate could directly act on CHRM1, FAAH, CNR2, SLC6A2, and SLC6A3, which were associated with anesthesia, attention deficit hyperactivity disorder, and major depressive disorder." (PMID 40729010, 2025). "However, the associations between these components and OPRM1, SLC6A3, and their therapeutic mechanisms for treating constipation and depression are reported here for the first time." (PMID 40910010, 2025). "Notably, PEOs modulate key targets such as SLC6A4 (serotonin transporter) and SLC6A3 (dopamine transporter), regulating serotonergic and dopaminergic synaptic pathways and thereby alleviating menopause-associated depression." (PMID 40238536, 2025). "Since fronto-striatal activity related to reward may be linked with neuropsychiatric PD symptoms, including impulsivity, apathy, and depression, it could be proposed that the SLC6A3 10/10 genotype or other SLC6A3 gene polymorphisms might be associated with PD-related depression." (PMID 37374342, 2023). "Furthermore, selective knockdown of TRPC6 in the mPFC-projecting VTA DA neurons (virus-retro carrying DIO-Trpc6-shRNA (TRPC6-rcKD) was injected into the mPFC of Slc6a3-Cre male mice) also conferred the mice with the depression- and anxiety-like behaviors." (PMID 39642080, 2024). "SLC6A3 genetic variations have been associated with depression risk in non-PD populations in some but not all studies." (PMID 37374342, 2023). "They found that individuals with the SLC6A3 3′UTR VNTR’s SS (9R/9R) genotype had a higher Beck Depression Inventory (BDI) depression scale (p = 0.022) and Hamilton Depression Rating Scale (HDRS or Ham-D) (p = 0.00001) score, in addition to a higher BMI (p = 0.001)." (PMID 37626766, 2023). "Depression is another potential factor that may confound the role of SLC6A3 in patients with LOAD." (PMID 28182634, 2017). "The molecular docking studies have elucidated potential interactions between the compounds of the SPZY formula and its two key targets in FC comorbid with depression, including OPRM1 and SLC6A3." (PMID 40910010, 2025). "The interaction between SLC6A3 and Medicarpin is identified as a crucial mechanism in the therapeutic efficacy of SPZY for treating FC comorbid with depression." (PMID 40910010, 2025). "In this study, we estimated the contribution of SLC6A4 (5HTT), HTR1A, HTR2A, HTR1B, SLC6A3 (DAT1), DRD4, DRD2, COMT, and BDNF genes to the suicidal behavior and severity of symptoms of depression and anxiety in the East-Slavic population of Russia." (PMID 34199792, 2021).